KLC2 (kinesin light chain 2)
Description:
Kinesin is a microtubule-associated force-producing protein that plays a role in organelle transport. The light chain functions in coupling of cargo to the heavy chain or in the modulation of its ATPase activity (Probable). Through binding with PLEKHM2 and ARL8B, recruits kinesin-1 to lysosomes and hence direct lysosomes movement toward microtubule plus ends.
Synonyms: FLJ12387
Tractability: Small molecule: it has a binding pocket of medium quality. Antibody: UniProt places it where antibodies can reach, with high confidence; its Gene Ontology location is reachable by antibodies, with high confidence. PROTAC: ubiquitination databases record sites on it; its protein half-life has been measured.
Gene: Protein-coding gene on chromosome 11 (66,257,294 to 66,267,860, forward strand). Ensembl gene ENSG00000174996.
Subcellular location: Cytoplasm, cytoskeleton; Lysosome membrane
Subcellular location (Human Protein Atlas): Cytosol; Plasma membrane; Mitochondria; Nucleoplasm
Pathways (Reactome):
Hemostasis: Kinesins
Immune System: MHC class II antigen presentation
Signal Transduction: RHO GTPases activate KTN1
Vesicle-mediated transport: COPI-dependent Golgi-to-ER retrograde traffic
Gene Ontology:
Molecular function: cadherin binding; protein binding; kinesin binding
Biological process: lysosome localization; microtubule-based movement
Cellular component: cytosol; lysosomal membrane; membrane; plasma membrane; protein-containing complex; cytoplasm; kinesin complex; kinesin I complex; cytoskeleton
Genetic constraint (gnomAD): Loss-of-function variants: 35 observed, 75.38 expected, observed/expected ratio (o/e) 0.46, 90% interval 0.35 to 0.62. The upper end of that interval is the gene's LOEUF score, 0.62, which puts it in group 2 of 6, group 1 being the genes least tolerant of losing a copy. Missense variants: 609 observed, 850.96 expected, observed/expected ratio (o/e) 0.72, 90% interval 0.67 to 0.76. Synonymous variants: 314 observed, 343.69 expected, observed/expected ratio (o/e) 0.91, 90% interval 0.83 to 1.
Homologues: Orthologues: chimpanzee KLC2 (99% identical), rat Klc2 (96% identical), macaque KLC2 (96% identical), mouse Klc2 (95% identical), guinea pig KLC2 (95% identical), pig KLC2 (93% identical). Paralogues in human: KLC4 (69% identical), KLC1 (68% identical), KLC3 (49% identical), NPHP3 (28% identical), APPBP2 (19% identical).
Diseases named in the same sentence as KLC2 in open-access papers:
KLC2 is named in the same sentence as 28 diseases in open-access papers, as found by Europe PMC text mining. Sharing a sentence is not in itself a finding about the gene and the disease. The quoted sentences say what the papers report.
Alzheimer disease (2 papers, 2019 to 2022). A progressive, neurodegenerative disease characterized by loss of function and death of nerve cells in several areas of the brain leading to loss of cognitive function such as memory and language. "Reduced levels of both KLC1 and KLC2 have been described in late stage Alzheimer’s disease cortex (Braak stage V/VI)." (PMID 31806024, 2019).
non-small cell lung carcinoma (2 papers, 2022 to 2023). A group of at least three distinct histological types of lung cancer, including non-small cell squamous cell carcinoma, adenocarcinoma, and large cell carcinoma. "Notably, overexpression of KLC2 was found in human HCC compared to non-neoplastic liver tissue in two independent cohorts, corroborating the previous observation that KLC2 is upregulated in non-small-cell lung cancer." (PMID 35563834, 2022).
bipolar disorder (1 paper, 2022). A disorder of the brain that causes unusual shifts in mood, energy, activity levels and the ability to carry out day-to-day tasks. "KLC2, PPP3CB, and CSMD1 were associated with mood disorders such as major depressive disorder or bipolar disorder." (PMID 35559016, 2022).
cervical cancer (1 paper, 2022). A primary or metastatic malignant neoplasm involving the cervix. "The genes which were being termed as an essential marker for significant prognosis of cervical cancer were ADRA1D, LTBP2 whereas KLC2 protein-protein was termed for poor prognosis in early NsCLC patients." (PMID 35057823, 2022).
Cognitive impairment (1 paper, 2022). Abnormal cognition is characterized by deficits in thinking, reasoning, or remembering. "CSMD1, PPP3CB, METTL7A, and KLC2 have been reported to be associated with cognitive impairment or cognitive performance." (PMID 35559016, 2022).
liver cancer (1 paper, 2022). An epithelial or non-epithelial malignant neoplasm that arises from the liver. "While a pro-tumorigenic role of STK39 and PHF19 has already been proposed in human HCC, the potential function of KLC2 in liver cancer has remained elusive and was thus investigated in more detail." (PMID 35563834, 2022). "In summary, LINC00152 and KLC2 are upregulated and co-expressed in liver cancer cells, providing further evidence that KLC2 is a player in the LINC00152-driven ceRNA network in human HCC." (PMID 35563834, 2022). "Although more investigations are needed to fully explore the functions of KLC2 in liver cancer, targeting of central effector proteins may be an alternative option for personalized HCC treatment." (PMID 35563834, 2022). "Thus, KLC2 exerts pro-tumorigenic functions in liver cancer cells." (PMID 35563834, 2022). "Using a LINC00152 knockout approach KLC2, PHF19, and STK39 were validated as being regulated by the LINC00152 ceRNA network in liver cancer." (PMID 35563834, 2022).
liver fibrosis (1 paper, 2022). "We did not observe an association between KLC2 expression and other clinical or pathological parameters (e.g., age, gender, performance status, progression-free or disease-specific survival, etiology, liver fibrosis stage, tumor grading, and vascular invasion; each p > 0.05)." (PMID 35563834, 2022).
meningioma (1 paper, 2023). A generally slow growing tumor attached to the dura mater. "Six antigens were exclusively found in the immunopeptidome of WHO grade I meningiomas (CAPN14, KIR2DS4, TMM44, ECD, CD86, and RFWD3), whereas WHO grade I and III meningiomas showed only one antigen in common (KLC2)." (PMID 37368072, 2023).
migraine (1 paper, 2023). "The resulting subnetwork included 9 genes: migraine-associated genes APOE, LRP1, CARF, CTIF, RNF213, and ECM1; LAMA2, which is associated with vestibular anomalies in mice; and the neurodevelopment-associated genes MYO5A and KLC2." (PMID 37107589, 2023).
optic atrophy (1 paper, 2022). A disorder characterized by loss of optic nerve fibers. "KLC2 may exert its function through factors involved in microtubule motor activity and kinesin binding and is associated with a variety of neurological diseases such as hereditary spastic diseases, optic atrophy, and SPOAN syndrome." (PMID 35559016, 2022).
virus infection (1 paper, 2015). "As before, F12-HA co-precipitated with KLC2 during virus infection, but only background levels were detected with KLC1." (PMID 25760349, 2015). "Interestingly F12, unlike A36, discriminated between different KLC isoforms, associating with KLC2 but not KLC1 and the F12/KLC2 association was only detectable in the presence of virus infection." (PMID 25760349, 2015).
cancer (6 papers, 2020 to 2025). A tumor composed of atypical neoplastic, often pleomorphic cells that invade other tissues. "In the COSMIC database, KLC2 mutations were distributed across the entire protein in different human cancer types; however, aside from the R312W mutation, two other mutations were recurrently detected in C-terminal–proximal regions in our cohort." (PMID 41502514, 2025). "Here, we provide the first evidence that upregulation of KLC2 promotes tumor growth in human cancer cells." (PMID 35563834, 2022). "The PT complex downregulated the gene expression of kinesin-1 light chain 2 (KLC2), mechanosensing PIEZO2, mitochondrial carrier homolog 2 (MTCH2), and ZDHHC14, which are known to enhance the invasion and migration of cancer cells." (PMID 38027033, 2023).
tumor (4 papers, 2021 to 2025). "We found that KLC2–R312W/L523I-transduced K562 cells demonstrated greater tumorigenic ability and higher tumor formation than KLC2-WT and EV control–transduced K562 cells." (PMID 41502514, 2025). "Here, we dissected the LINC00152-driven ceRNA network in human HCC and identified miR-143a-3p and KLC2 as new players promoting tumor growth of human HCC." (PMID 35563834, 2022). "Of relevance, KLC2 was co-expressed with LINC00152 mRNA specifically in human HCC cells, demonstrating a tumor cell-specific mechanism, and independently validating the upregulation of both KLC2 and LINC00152 in an independent human HCC cohort." (PMID 35563834, 2022). "However, the suppression of tumor growth with imatinib was greater in KLC2-WT mice than in the control and L523I mice on the 15th day of the treatment, with reductions of 39% and 25% observed in mice carrying KLC2-WT and L523I, respectively." (PMID 41502514, 2025). "This comprehensive approach facilitated the identification of a LINC00152-driven ceRNA network in human HCC, in which the limited bioavailability of miR-143a-3p leads to upregulation of Kinesin Light Chain 2 (KLC2) and consequently increased tumor cell proliferation and migration." (PMID 35563834, 2022).
infection (2 papers, 2015 to 2017). The state of being infected such as from the introduction of a foreign agent such as serum, vaccine, antigenic substance or organism. "In the absence of VACV infection KLC2 co-precipitated with F12 at levels only marginally above background." (PMID 25760349, 2015). "Infection of cells in which KLC2 was knocked down had no discernible effect on plaque size or virus egress to the cell surface as measured by surface B5 staining and flow cytometry, despite the F12/E2 complex interacting with KLC2." (PMID 25760349, 2015). "Using full‐length KLCs and a full‐length A36 expressed at natural levels during infection, the interaction was specific for KLC1 and practically absent from KLC2." (PMID 28485852, 2017).
haematological disorders (1 paper, 2021). "In contrast, to the best of our knowledge, mutations in PHIP and KLC2 have not been reported in the context of haematological disorders." (PMID 33990592, 2021).
myopathy (1 paper, 2022). A disease of the muscle in which the muscle fibers do not function properly. "Forty-six candidate genes are prioritized by multiple approaches (42 for LST and 6 for MVPA; 2 overlap) and point to endocytosis (CNIH2, RAB1B, KLC2, PACS1, REPS1, DNM3, EXOC4), locomotion (CADM2, KLC2) and myopathy (MLF2, HERC1, KLC2, SIL1) as relevant pathways." (PMID 36071172, 2022).
KLC2 also shares sentences with these, for which no sentence is quoted: Sepsis (2 papers); amyotrophic lateral sclerosis (1); Anxiety (1); Chronic Myeloid Leukemia (1); hematological neoplasms (1); hydatidosis (1); major depressive disorder (1); mood disorder (1); neurological diseases (1); prion disease (1); prostate carcinoma (1); SPOAN syndrome (1).